APP (amyloid beta precursor protein)
Diseases named in the same sentence as APP in open-access papers (continued):
Sharing a sentence is not in itself a finding about the gene and the disease.
delirium (5 papers, 2020 to 2024). A disorder characterized by confusion; inattentiveness; disorientation; illusions; hallucinations; agitation; and in some instances autonomic nervous system overactivity. "The misregulation of the four HAR-Brain genes, namely APP, PLCB1, NPY, and HTR2A, in the M1 module is more likely to underlie delirium susceptibility rather than specifically be the molecular pathways driving the development of delirium." (PMID 33086708, 2020). "We found that four of the HAR-Brain genes, namely APP, PLCB1, NPY, and HTR2A, in the M1 module were highly connected and appeared to exhibit hub properties, which might play vital roles in delirium development." (PMID 33086708, 2020).
frontotemporal dementia with parkinsonism (5 papers, 2017 to 2025). "Familial AD (FAD) is caused by abnormal processing or overexpression of APP, whereas frontotemporal dementia with parkinsonism related to chromosome 17 (FTDP-17) is caused by tau mutations that result in AD-like hyperphosphorylation and neurofibrillary tangles (NFTs)." (PMID 40027104, 2025).
hemorrhage (5 papers, 2015 to 2023). Loss of blood from the vascular compartment to the exterior or into nonvascular body space as a result of rupture or severance of the blood vessels. "These mutations occur within the APP gene and are associated with cerebral hemorrhages both in the presence (Ala692Gly) and absence (Glu693Gln) of AD pathology." (PMID 37429916, 2023). "In cases of fAD caused by Dup–APP, it has been reported that hemorrhaging is more frequent than in elderly DS subjects, suggesting a link between APP and excess release of heme iron that is dampened by other chromosome 21 gene products." (PMID 30823541, 2019). "A similar positive correlation between the retina and brain was observed for the number of non-hemorrhage associated diffuse axonal lesions (r = 0.3; p = 0.04) and for the area (r = 0.38; p = 0.01) of β-APP staining." (PMID 25853095, 2015).
inclusion body myositis (5 papers, 2011 to 2022). A slowly progressive degenerative inflammatory disorder of skeletal muscles characterized by late onset weakness of specific muscles and distinctive histopathological features. "The cleavage of APP, APP overexpression, and the consequences of APP mutations have been well studied in the brain and muscle for AD pathogenesis and inclusion body myositis, respectively." (PMID 22912823, 2012). "Aβ-containing structures as well as epitopes containing APP were described in some cases of inclusion-body myositis, the collection of diseases that are characterized by the vacuoles and filamentous inclusions in muscle fibers." (PMID 29018812, 2017). "In addition to its well-documented roles in neurodegeneration, APP and its cleaved products have been also implicated in other diseases, most notably sporadic inclusion body myositis (s-IBM), the most common skeletal muscle disorder of the elderly." (PMID 21518451, 2011). "Similarly, APP is involved in the generation of proteinaceous inclusions observed in muscle tissue as the result of inclusion body myositis." (PMID 22912823, 2012). "The same group also suggested that, during the course of the disease, the blood might produce Aβ and APP during inclusion-body myositis and all other inflammatory myopathies, as they found that human muscle macrophages express APP and have all the necessary machinery for its production." (PMID 29018812, 2017).
Lesch-Nyhan disease (5 papers, 2017 to 2025). "Given that APP is one of the proteins implicated in both AD and Lesch-Nyhan diseases, it has been speculated that the genetic diversity originated by the alternative splicing mechanism could potentially explain the clinical diversity and complexity of these diseases." (PMID 28798312, 2017). "For such a purpose, the Lesch-Nyhan disease (LND) has been selected as a valuable model to study the genetic-epigenetic interplay, especially to explore the epistasis between the housekeeping hypoxanthine phosphoribosyltransferase 1 (HPRT1) and β-amyloid precursor protein (APP) genes." (PMID 40717738, 2025).
lipid metabolism disorder (5 papers, 2020 to 2025). "APOE and APP are the most commonly accepted risk genes for early onset of AD, suggesting the involvement of lipid metabolism disorder in AD progression." (PMID 32224504, 2020). "The effect of GBLE on lipid metabolism disorder in APP/PS1 mice was similar to but slightly weaker than that of donepezil." (PMID 36618950, 2022). "Lipid metabolism disorders enhance Aβ production by regulating the APP processing pathway; excess lipids activate the cleavage activity of β-secretase and γ-secretase, leading to abnormal APP hydrolysis and excessive Aβ peptide generation." (PMID 41300478, 2025). "In summary, Akk supplementation can regulate lipid metabolism disorders in APP/PS1 mice." (PMID 32321934, 2020). "In addition, 9-month-old APP/PS1 mice developed significant lipid metabolism disorders, evidenced by increasing levels of serum Chol and TG (p < 0.05, respectively), and fat accumulation in the liver, which was similar between the high-fat diet group and normal diet group." (PMID 32321934, 2020).
liver cancer (5 papers, 2019 to 2025). An epithelial or non-epithelial malignant neoplasm that arises from the liver. "It has previously been shown in hepatic cancer cell lines that APP overexpression contributes to the resistance of liver cancer cells to 5-FU." (PMID 38391955, 2024). "The results indicated that the key targets of the pathway in cancer were related to the therapeutic effect of anti-liver cancer activities, including SRC, EGFR, ESR1, PTGS2, and APP." (PMID 36561345, 2022).
microcephaly (5 papers, 2021 to 2023). A congenital or acquired developmental disorder in which the circumference of the head is smaller than normal for the person's age and sex. "In another child, a nonsense mutation in Ox-2 antigen domain of APP was associated with microcephaly, seizures, bilateral cataracts truncal hypotonia with spastic quadriparesis." (PMID 37808474, 2023). "A clinical case of a homozygous nonsense truncating mutation in APP leading to microcephaly has been reported." (PMID 37327344, 2023). "For example, homozygous nonsense mutations in APP found in a child was associated with microcephaly, decreased somatic growth, hypotonia, developmental delay, thinning of the corpus callosum, and seizures." (PMID 37808474, 2023). "Recently reported patients harbouring homozygous non-sense mutations in APP display microcephaly and a reduced corpus callosum, supporting a role of APP in axonal outgrowth." (PMID 35360155, 2022). "Nevertheless, and suggestive of a possibly more prominent role of APP for human brain physiology, an infant with a homozygous truncating mutation in the APP N‐terminus was reported to show developmental delay, microcephaly, callosal dysgenesis, and seizures." (PMID 34008862, 2021). "APP abnormality, per say, may be causal as significant mutations in the APP gene have been associated with microcephaly." (PMID 37808474, 2023). "However, this contradicts the many other associations between the anabolic APP processing path, which produces sAPPα, the associated P3, and a tendency far more toward macrocephaly than microcephaly." (PMID 37808474, 2023). "The exact mechanism that APP and derivatives additionally contribute to autistic features seen in conditions of microcephaly remains to be discovered." (PMID 37808474, 2023). "T21 is a condition wherein microcephaly is a universal phenotype and APP is in abundance as APP localizes to chromosome 21 which is triplicated in T21." (PMID 37808474, 2023). "APP and Aβ are only beginning to be studied in neurodevelopmental disorders of acquired microcephaly such AS and dup15q11-q13 where P3 has been detected as a potentially neuroprotective response to accumulation of Aβ peptide." (PMID 37808474, 2023). "Genetic causes of congenital microcephaly will first be described to highlight known mechanisms contributing to microcephaly to understand how APP metabolites, particularly Aβ can reduce brain development." (PMID 37808474, 2023). "As demonstrated by increased APP expression in the T21 prototype, resulting in excessive APP metabolites, especially Aβ peptides, may contribute to microcephaly via disruption in neurogenesis, elongated G1/S cycle, arrested cell cycle, promoting apoptosis." (PMID 37808474, 2023). "Uncovering APP’s role in syndromic ASD may lead to identification of common pathways that impact nonsyndromic ASD with microcephaly." (PMID 37808474, 2023). "Finally, APP metabolites, including Aβ as studied in other genetic conditions associated with ASD with microcephaly will be presented." (PMID 37808474, 2023). "This sets the stage for addressing how APP, particularly Aβ, may contribute to microcephaly in ASD." (PMID 37808474, 2023). "Future work could focus on specific routes APP may take to directly affect centrosomes by way of CDKRAP2, which has been associated with microcephaly, such as the astral microtubular pathway that directs proteins from the nuclear membrane to the centrioles that comprise the centrosome." (PMID 37808474, 2023). "We have proposed a role for APP and in particular nonamyloidogenic sAPPα, in brain overgrowth and macrocephaly in ASD, and presently we look to the amyloidogenic pathway to explain microcephaly in ASD." (PMID 37808474, 2023).
motor neuron disease (5 papers, 2011 to 2025). "Several findings suggest that the amyloid precursor protein (APP) and the amyloid cascade may play a role in motor neuron disease (MND)." (PMID 27877154, 2016). "From these previous results we concluded that the presence of enlarged APP-positive vesicles could be indicative for motor neuron diseases with impaired retrograde protein transport." (PMID 21385376, 2011).
Niemann-Pick disease type C (5 papers, 2012 to 2024). NPC is a complex lipid storage disease mainly characterized by the accumulation of unesterified cholesterol in the late endosomal/lysosomal compartment. "These and other features such as upregulation of the amyloid precursor protein (APP) and increase in certain oxysterols were reminiscent of Niemann-Pick disease type C (NPCD)." (PMID 34638955, 2021). "APP is a disease modifier of Niemann-Pick disease type C (NPC)." (PMID 31847862, 2019).
steatosis (5 papers, 2016 to 2024). Increased lipid within the cytoplasm of cells. "Overall, alcohol-induced changes to hepatic LRP1 and APP occurred within a wide range of liver injury and steatosis." (PMID 36187787, 2022). "We observed multifocal hepatitis and substantial steatosis in WT and APP-Tg mice fed with HFD, whereas the livers of mice fed with SD were devoid of hepatitis or steatosis." (PMID 26728181, 2016). "Only in APP/PS1 mice fed a HFD was the increase in steatosis statistically significant." (PMID 37686722, 2023). "Furthermore, APP/PS1 mice fed a HFD developed a significant gain in steatosis at 6 months compared to WT mice fed a HFD." (PMID 37686722, 2023). "In addition to upregulation of APP, the downregulation of LRP1 associated with steatosis is likely to significantly impact the ability of the liver to clear Aβ from the periphery." (PMID 36187787, 2022). "Four weeks of intragastric alcohol feeding to mice, which causes significant fatty liver (steatosis) and liver injury, caused no changes in AD pathology markers in the brain [amyloid precursor protein (APP), presenilin], except for a decrease in microglial cell number in the cortex of the brain." (PMID 36187787, 2022). "First, we analyzed the accumulation of fat deposition (steatosis) in the liver after 1 year of HFD treatment in both WT and APP-Tg mice." (PMID 26728181, 2016). "Furthermore, mRNA expression levels of APP-processing genes were plotted in liver samples from patients with an MAS ≥ 1, indicating steatosis or MASH, stratified according to their histological fibrosis score." (PMID 39201455, 2024). "We used a TaqMan RT-PCR-based high-throughput platform to analyze a variety of genes involved in APP and Aβ-42 metabolism in liver samples from patients with an MAS of 1–4 (steatosis) or 5–8 (MASH), and from patients with histopathologically proven non-diseased livers (MAS = 0)." (PMID 39201455, 2024). "The deposition of lipids and steatosis accompanied by oxidative stress are responsible for the regulation of genes involved in APP and Aβ metabolism, but have no implication on hepatic Aβ-42 levels." (PMID 39201455, 2024). "Modulation of hepatic LRP1 and APP does not seem alcohol-specific, as ob/ob mice with significant steatosis also had declines in LRP1 and increases in APP expression in the liver." (PMID 36187787, 2022). "Since obese mice (ob/ob) with extensive steatosis also demonstrated decreases in hepatic LRP1 and an increase in hepatic APP, we believe steatosis or liver injury rather than alcohol are directly responsible for the modulation of these key proteins involved in maintaining Aβ homeostasis." (PMID 37298443, 2023). "However, ob/ob mice and NAFLD are associated with some increases in ALT and liver injury, so the distinction between liver injury and steatosis in the regulation of hepatic LRP1 and APP may be difficult to untangle." (PMID 36187787, 2022). "We next examined whether the downregulation of hepatic LRP1 and upregulation of hepatic APP was alcohol specific or due to liver pathology by investigating a non-alcohol model of steatosis, ob/ob mice." (PMID 36187787, 2022). "Thus, signaling pathways involved in triggering steatosis and signaling pathways altered by lipid accumulation during steatosis could be involved in regulation of LRP1 and APP." (PMID 36187787, 2022).
type 1 diabetes mellitus (5 papers, 2020 to 2024). A chronic condition characterized by minimal or absent production of insulin by the pancreas. "Interestingly, pathways associated with metabolism such as type I diabetes mellitus and glycerolipid metabolism were found to be upregulated in APP-KI microglia and rescued in APP-KI; C3aR-KO microglia." (PMID 37317973, 2023).
acute myeloid leukemia (4 papers, 2021 to 2024). Acute myeloid leukemia (AML) is a group of neoplasms arising from precursor cells committed to the myeloid cell-line differentiation. "Because homozygous Spi1-knockdown mice also become moribund from T-cell lymphoma and acute myeloid leukemia starting at 3 months of age10, we utilized only Spi1 heterozygous knockdown (Spi1+/−;APP/PS1) mice and wild-type for Spi1 (Spi1+/+;APP/PS1) mice." (PMID 38734693, 2024). "It should be noted that APP is highly expressed in acute myeloid leukemia (AML), which may promote cancer cell proliferation and metastasis." (PMID 33777800, 2021).
anemia (4 papers, 2014 to 2019). A reduction in the number of red blood cells, the amount of hemoglobin, and/or the volume of packed red blood cells. "Individuals suffering from Dup–APP and DS are associated with increased APP levels and have yet to be investigated for localized anemia in affected neurons." (PMID 30823541, 2019). "We would note, based on APP’s iron export function, the presence of three copies of APP gene can be predicted to cause excess cellular iron efflux and a local mis-queued anemia in affected cell types, including neurons of the DS individuals." (PMID 30823541, 2019). "Posiphen is undergoing clinical trials as an APP translation blocker that generates anti-amyloid efficacy and may also cause measurable anemia and would necessitate co-treatment with iron supplements." (PMID 30823541, 2019).
aortic atherosclerosis (4 papers, 2014 to 2020). A atherosclerosis that involves the aorta. "Interestingly, selective overexpression of mutated human APP in the brain accelerated aortic atherosclerosis in ApoE-deficient mice." (PMID 32987857, 2020). "Expression of AD-related APP in a strain of ATH-prone mice led to aortic atherosclerosis, and atherosclerotic lesions in Apoe knockout mice were significantly increased by overexpression of AD-related mutant APP (APPAD mice)." (PMID 24656052, 2014). "In addition, APP and Aβ are detected in human carotid plaques and atherosclerotic aortas, and overexpression of APP accelerates, whereas deletion partially protects against, the development of aortic atherosclerosis in APOE–/– mice." (PMID 32407295, 2020).
asthma (4 papers, 2010 to 2025). "This link between APP and asthma-associated genes suggests potential relationship between AD and asthma that will be further discussed." (PMID 28428554, 2017). "APP, in turn, is cleaved by an asthma susceptible gene called ADAM33." (PMID 20513247, 2010). "Recently, it has been reported that a peptide derived from APP is cleaved by α disintegrin and metalloproteinase 33 (ADAM33), which is an asthma susceptibility gene." (PMID 20513247, 2010). "There has been a report that APP is cleaved by α disintegrin and metalloproteinase 33 (ADAM33), which is an asthma susceptibility gene." (PMID 20513247, 2010). "The link between APP and asthma genes, as highlighted in our module, can open new routes of research for elucidating the functional role and relationships of these genes in asthma, and also potentially, in AD." (PMID 28428554, 2017).
Ataxia (4 papers, 2014 to 2022). Ataxia refers to impaired coordination of voluntary muscle movement. "Differently, patients with APP mutation in this study also presented with EPS, spastic paraparesis, pathologic reflex, and ataxia." (PMID 36313020, 2022). "Aplp2 knockout mice were normal in size, fertile, and appeared healthy, whereas 80% of Aplp2/APP double knockout animals died within 24 h after birth and the remaining 20% exhibited difficulty in righting, ataxia, spinning behavior, and a head tilt." (PMID 26313004, 2015). "Some patients with APP mutations (e.g., A673V, A692G, and E693del) described neurological symptoms such as extrapyramidal symptoms (EPS), myoclonus, seizures, spastic paraplegia, and ataxia." (PMID 36313020, 2022).
breast tumor (4 papers, 2014 to 2017). "The high degree of APP exon 8 excision in breast tumor versus normal tissue (p<10−5) prompted its inclusion in a 12-marker APP splice variant panel that correctly identified 33 of 35 (96%) of tumor samples in a blinded validation assay." (PMID 26840089, 2016). "The neurogenes APP and EFNB1 are upregulated in basal and HER2-enriched breast tumors meanwhile NGFR is upregulated only in basal-like breast tumors." (PMID 26673618, 2016).
cerebral infarction (4 papers, 2013 to 2024). An ischemic condition of the brain, producing a persistent focal neurological deficit in the area of distribution of the cerebral arteries. "Whether liraglutide could suppress the activation of GSK-3β by modulating the APP metabolism to hinder Aβ generation in the regions away from the primary lesion after cerebral infarction needs further elucidation." (PMID 30618584, 2018). "The glymphatic function in the cortex surrounding cerebral infarction was determined using tracer, glial fibrillary acid protein (GFAP), AQP4 co-staining, and beta-amyloid precursor protein (APP) staining; differential genes were detected using RNA-seq." (PMID 37695472, 2024).